HNRNPL (heterogeneous nuclear ribonucleoprotein L)
Diseases named in the same sentence as HNRNPL in open-access papers (continued):
Sharing a sentence is not in itself a finding about the gene and the disease.
pancreatic cancer (7 papers, 2016 to 2024). "Transwell migration assays showed that the migration rate of negative control cells was greater than that PATU8988T and BXPC-3 cells depleted of HNRNPL by shRNA, indicating that HNRNPL deficiency impaired the migration ability of pancreatic cancer cells." (PMID 31355266, 2019). "Pan, L. discovered that tRF-21 can bind to Ser52 within the Gly-rich domain of the oncogenic RNA-binding protein heterogeneous nuclear ribonucleoprotein L (hnRNP L) in pancreatic cancer." (PMID 39659673, 2024). "IHC staining indicated that HNRNPL was primarily expressed within the nuclei of pancreatic cancer cells." (PMID 31355266, 2019). "We further examined the effects of HNRNPL on the pancreatic cancer cell cycle and revealed that downregulation of HNRNPL resulted in G1-phase cell cycle arrest in PC cells." (PMID 31355266, 2019). "This manuscript screened out all of the commonly upregulated HNRNPs in TCGA-PAAD and GSE16515 by Venn diagram and determined that HNRNPA2B1 and HNRNPL were upregulated in pancreatic cancer tissues as compared with normal pancreas tissues." (PMID 31355266, 2019). "In conclusion, this study utilizes several cohorts to identify the generally overexpressed HNRNPs, HNRNPL, in PC and demonstrates that downregulation of HNRNPL inhibits pancreatic cancer progression." (PMID 31355266, 2019). "Based on these results, we investigated the effect of HNRNPL expression on the pancreatic cancer cell cycle." (PMID 31355266, 2019). "Moreover, public databases were explored to study potential molecular mechanisms of HNRNPL in pancreatic cancer." (PMID 31355266, 2019). "The RNA splicing factor HNRNPL is involved in the repression or activation of exon inclusion in targeted genes, and its high expression consistently correlated with unfavorable prognosis in renal cancer (p < 0.001), liver cancer (p < 0.001), and pancreatic cancer (p < 0.001)." (PMID 31925297, 2020). "For example, 21 nt i-tRF-Gly interacts with hnRNPL and then prevents phosphorylation of hnRNPL by AKT2, thereby reducing the AKT2-hnRNAPL-DDX17 axis and attenuating the malignant phenotype in pancreatic cancer cells." (PMID 36360311, 2022). "Our results clearly demonstrated that knockdown of HNRNPL could markedly repress the migration ability and repress the EMT process by downregulating N-cadherin and up-regulating E-cadherin in pancreatic cancer cells." (PMID 31355266, 2019). "Thus, we concluded that HNRNPL was commonly overexpressed in pancreatic tumor tissues compared with noncancerous tissues in multiple public databases." (PMID 31355266, 2019). "Experiments in vitro were performed to discover that downregulation of HNRNPL could impede the migration ability and EMT process in PC cell lines, while it could not inhibit proliferation of pancreatic cancer cells." (PMID 31355266, 2019). "To further test the expression patterns of HNRNPL and HNRNPA2B1 in PC, we employed one Oncomine dataset and found that HNRNPL was statistically higher in pancreatic cancer as opposed to normal tissues, while HNRNPA2B1 was not significantly upregulated in Segara Pancreas." (PMID 31355266, 2019).
gastric cancer (5 papers, 2020 to 2025). A primary or metastatic malignant neoplasm involving the stomach. "In a recent study, HNRNPL was identified as a prognostic biomarker associated with microsatellite instability in gastric cancer, suggesting that it may be a new target for the treatment of MSI gastric cancer." (PMID 39023715, 2024).
liver cancer (5 papers, 2019 to 2021). An epithelial or non-epithelial malignant neoplasm that arises from the liver. "A recent study have demonstrated that HNRNPL was highly expressed in HCC samples and down-regulation of HNRNPL expression can significantly inhibit the proliferation and migration of liver cancer cells, which was in accordance with our results." (PMID 31844595, 2019). "In addition, upregulation of typical splicing proteins such as SRSF2, hnRNPL, hnRNPA2, hnRNPA2B1 and hnRNPAB were previously observed in liver cancers 33-37, although their misregulated splicing events have not been fully identified." (PMID 32483414, 2020).
oral squamous cell carcinoma (4 papers, 2016 to 2019). "For instance, as a multi-functional splicing factor, HNRNPL (heterogeneous nuclear ribonucleoprotein L) is overexpressed in oral squamous cell carcinoma and promotes expression of the full-length oncogenic SRSF3 protein." (PMID 28257090, 2017).
ovarian carcinoma (4 papers, 2011 to 2025). A malignant neoplasm originating from the surface ovarian epithelium. "FBXO16 was able to suppress the proliferation, clonogenic survival, and cell invasion of ovarian cancer cells by mediating hnRNPL degradation and failure to destruct hnRNPL caused uncontrol malignant behavior of ovarian cancer cells." (PMID 34333526, 2021). "We found that treatment with the proteasome inhibitor MG132 increased hnRNPL protein levels in several ovarian cancer cells." (PMID 34333526, 2021). "Failure to degrade hnRNPL promoted ovarian cancer cell proliferation in vitro and tumor growth vivo, phenocopying the deficiency of FBXO16 in ovarian cancer." (PMID 34333526, 2021). "Together, these results suggest FBXO16 controls the ubiquitination and degradation of hnRNPL in ovarian cancer." (PMID 34333526, 2021). "In this study, FBXO16 was identified as an adaptor protein of a SCF E3 ligase complex that regulates the ubiquitination and degradation of its substrate protein hnRNPL in ovarian cancer." (PMID 34333526, 2021). "Depletion of hnRNPL is sufficient to inactive multiple oncogenic signaling regulated by FBXO16 and prevent the malignant behavior of ovarian cancer cells caused by FBXO16 deficiency." (PMID 34333526, 2021). "It will be interested to investigate whether the FBXO16/hnRNPL axis also regulates the stability of Bcl-2 mRNA in ovarian cancer in the future." (PMID 34333526, 2021). "To investigate whether hnRNPL mediates the role of FBXO16 in ovarian cancer, we further used the CRISPR/Cas9 system to knockdown hnRNPL and FBXO16 individually or simultaneously." (PMID 34333526, 2021). "More importantly, stable expressing a hnRNPLΔRRM3 mutant that cannot be recognized and degraded by FBXO16 phenocopied FBXO16 deficiency in ovarian cancer cells, indicating FBXO16 promotes the proliferation and invasion of ovarian cancer cells mainly via hnRNPL degradation." (PMID 34333526, 2021). "We next performed Immunohistochemistry (IHC) analysis to evaluate the potential association between FBXO16 and hnRNPL in 68 human ovarian cancer specimens and a negative correlation between FBXO16 and hnRNPL proteins was observed in those ovarian cancer specimens (χ2 = 14.81, P < 0.001)." (PMID 34333526, 2021). "The protein levels of hnRNPL, but not its mRNA levels, were significantly increased in FBXO16 silenced or depleted ovarian cancer cells, suggesting the regulation of hnRNPL by FBXO16 occurs at the post-transcriptional level." (PMID 34333526, 2021).
colon cancer (3 papers, 2021 to 2024). "Cancer metastasis-associated long intergenic non-coding RNA (CALIC) has been shown to associate with the RNA-binding protein heterogeneous nuclear ribonucleoprotein-L (hnRNP-L) to upregulate Axl, leading to the promotion of migration and metastasis in colon cancer cells." (PMID 33806258, 2021). "CALIC associates with the RNA‐binding protein heterogeneous nuclear ribonucleoprotein L (hnRNP‐L) and upregulates AXL, thereby promoting migration and metastasis of colon cancer cells." (PMID 34778084, 2021).
neuroblastoma (3 papers, 2023 to 2026). Neuroblastoma (NB) is the most common solid, extracranial childhood tumor. "Coincidentally, the highest SNHG1 binding protein score in neuroblastoma also includes YBX1 (and also HnRNPL and MATR3), where the role of HnRNPL interacting with SNHG1 in PCa has been demonstrated." (PMID 41507135, 2026).
prostate tumor (3 papers, 2021 to 2024). "We previously discovered that heterogeneous nuclear ribonucleoprotein L (HnRNP-L), a multi-functional RBP, is associated with pro-proliferation and anti-apoptosis activities in prostate tumor cells." (PMID 34760337, 2021). "We have discovered that heterogeneous nuclear ribonucleoprotein L (HnRNP-L), a multi-functional RBP, is associated with pro-proliferation and anti-apoptosis activities in prostate tumor cells." (PMID 34760337, 2021).
esophageal squamous cell carcinoma (2 papers, 2022 to 2023). Esophageal squamous cell carcinoma (ESCC) is a type of esophageal carcinoma (EC) that can affect any part of the esophagus, but is usually located in the upper or middle third. "CASC8 is an oncogene that can delay the progression of esophageal squamous cell carcinoma by binding directly to hnRNPL and preventing it from being degraded by ubiquitin-mediated processes." (PMID 36672865, 2023).
osteosarcoma (2 papers, 2019 to 2021). A usually aggressive malignant bone-forming mesenchymal neoplasm, predominantly affecting adolescents and young adults. "One investigation showed that LEF1-AS1 is upregulated in osteosarcoma with capability to enhance cell proliferation and to stimulate Wnt pathway by sponging heterogeneous nuclear ribonucleoprotein L (HNRNPL) to stabilize mRNA of LEF1." (PMID 34130697, 2021). "Moreover, the effect of LEF1-AS1 deletion could be partially rescued by LEF1 overexpression, which further confirmed a regulatory loop of LEF1-AS1/HNRNPL/LEF1-AS1 in osteosarcoma." (PMID 34130697, 2021).
retinoblastoma (2 papers, 2023). A malignant tumor that originates in the nuclear layer of the retina. "For example, lncRNA transcript RBAT1 recruits hnRNPL to the promoter of oncogene E2F3 to ci-activate its transcription, resulting in the tumorigenesis of retinoblastoma." (PMID 37741985, 2023).
allergic asthma (1 paper, 2025). A asthma with a basis in a pathological type I hypersensitivity reaction. "Other identified genes, such as TARDBP, TENT4B, and HNRNPL, have not been previously implicated in allergic asthma." (PMID 40504147, 2025).
amyotrophic lateral sclerosis (1 paper, 2025). Amyotrophic lateral sclerosis (ALS) is a neurodegenerative disease characterized by progressive muscular paralysis reflecting degeneration of motor neurons in the primary motor cortex, corticospinal tracts, brainstem and spinal cord. "Our bioinformatics analysis revealed that the interaction network composed of LILRA5, HNRNPL and AGBL3 was significantly enriched in functions such as’ RNA splicing regulation ‘and’ metal peptidase activity ‘, and was closely related to the ‘amyotrophic lateral sclerosis pathway (hsa05014)’." (PMID 41379792, 2025).
atherosclerosis (1 paper, 2023). A disease characterized by the build-up of fatty material and calcium deposition in the arterial wall resulting in partial or complete occlusion of the arterial lumen. "In addition, we may speculate that in atherosclerosis hnRNPL downregulation may have a positive effect in reducing inflammation and the accumulation of cells and extracellular matrix between the vessel endothelium and tunica media." (PMID 37570694, 2023). "Although its role has to be defined in SMC phenotype determination and atherosclerosis development, the hnRNPL decrease may concur, according to the several processes it modulates in different cell types, to the cytostatic effect of furoxan treatment on in vitro SMCs." (PMID 37570694, 2023).
chronic lymphocytic leukemia (1 paper, 2019). "Here we show that the heterogeneous nuclear ribonucleoprotein L (HNRNPL) binds to the polymorphic marker D2S1888 at the 3′UTR of BUB1 gene, impairs the miR-155 targeting, and restores BUB1 expression in chronic lymphocytic leukemia." (PMID 31018621, 2019).
diabetes (1 paper, 2025). "Previous studies have shown that the expression of HNRNPL is increased in diabetes, and its high expression has negative effects on endothelial cells." (PMID 40758539, 2025).
endometrial cancer (1 paper, 2025). Primary or metastatic malignant neoplasm involving the endometrium (mucous membrane that lines the endometrial cavity). "Some DNA-binding proteins such as heterogeneous nuclear ribonucleoprotein L (HNRNPL), heterogeneous nuclear ribonucleoprotein U (HNRPU), and interleukin enhancer binding factor 2 (ILF2) are closely associated with endometrial cancer." (PMID 40575382, 2025).
Epileptic encephalopathy (1 paper, 2018). A condition in which epileptiform abnormalities are believed to contribute to the progressive disturbance in cerebral function. "The top-ranked probes related to 25 genes including HNRNPL, RASSF5, CD3D and KALRN involved in immune signalling pathways, in addition to TBC1D24, FBXO9 and VIPR2 previously linked to epileptic encephalopathy." (PMID 29484035, 2018).
Ewing sarcoma (1 paper, 2021). A small round cell tumor that lacks morphologic, immunohistochemical, and electron microscopic evidence of neuroectodermal differentiation. "Our analysis identified TRIM25, APP, ELAV1, RNF4, and HNRNPL as ideal mRNA targets for Ewing sarcoma therapy." (PMID 34662337, 2021).
glaucoma (1 paper, 2021). Increased pressure in the eyeball due to obstruction of the outflow of aqueous humor. "These RNA‐binding proteins (or their closely related family members) have demonstrated important roles in RNA‐regulation (including splicing, export, stability, polyadenylation, and translation); in addition, SRSF3 and HNRNPL showed associations with ocular disease, mainly glaucoma." (PMID 33973683, 2021).
heart failure (1 paper, 2022). Inability of the heart to pump blood at an adequate rate to meet tissue metabolic requirements. "All 14 RBPs differentially expressed between heart failure and healthy adult heart were also significantly differentially expressed between iPSC-CVPC and healthy adult heart, although three had opposite directions of effect (HNRNPL, MBNL1, SAMD4A)." (PMID 35226669, 2022).
hyperglycaemia (1 paper, 2025). "Similarly, our research indicates that HNRNPL is highly expressed under hyperglycaemia metabolic memory conditions." (PMID 40758539, 2025).
invasive breast carcinoma (1 paper, 2025). A carcinoma that infiltrates the breast parenchyma. "Among the family of heterogenous nuclear ribonucleoproteins, HNRNPL is one of the few for which increased expression is associated with a worse overall survival in invasive breast carcinoma." (PMID 40060410, 2025).
Kawasaki disease (1 paper, 2020). A rare inflammatory disease characterized by an acute febrile, systemic, self-limiting, medium-vessel vasculitis primarily affecting children. "The lincRNA THRIL, whose expression levels correlated with the severity of Kawasaki disease, induced expression of TNF-α by forming a ribonucleoprotein (RNP) complex with hnRNPL." (PMID 32929606, 2020).
latent infection (1 paper, 2021). "On the other hand, a dramatic increase in latent infection was seen after knockdown of TOP2A, SRP14, HNRNPH1, DDX1, and HNRNPL (blue bars)." (PMID 34194479, 2021).
leukemia (1 paper, 2013). A malignant (clonal) hematologic disorder, involving hematopoietic stem cells and characterized by the presence of primitive or atypical myeloid or lymphoid cells in the bone marrow and the blood. "These genes, including HNRNPL, EIF4H and PSMA1, were validated by qRT-PCR for use as control genes in leukemia." (PMID 24069164, 2013).
membranous nephropathy (1 paper, 2021). "hnRNPL impacts the pathological conditions of membranous nephropathy by stabilizing the MTNR1A transcript." (PMID 33461173, 2021).
osteoporosis (1 paper, 2025). A condition of reduced bone mass, with decreased cortical thickness and a decrease in the number and size of the trabeculae of cancellous bone (but normal chemical composition), resulting in increased fracture incidence. "After identifying LILRA5, HNRNPL, and AGBL3 as common hub genes for Osteoporosis and stroke, their synergistic regulatory mechanisms further confirm the molecular basis of comorbidity." (PMID 41379792, 2025). "Bioinformatics analysis identified LILRA5, HNRNPL and AGBL3 as common key genes for Osteoporosis and stroke, and these genes were highly effective in diagnosing both diseases." (PMID 41379792, 2025).
rectal cancer (1 paper, 2025). A primary or metastatic malignant neoplasm that affects the rectum. "HNRNPL is highly expressed in both rectal cancer tumor tissue and NACR resistance group, suggesting that reducing the expression of HNRNPL in LACR may increase the sensitivity of patients to NACR, thus achieving a better prognosis." (PMID 40770782, 2025).
rheumatic diseases (1 paper, 2021). "Among these proteins, U1–70K (Snrnp70) is the target of self-reactive B cells and T cells in several rheumatic diseases, Ptbp1 is essential for B cell ontogeny and B cell receptor (BCR)-mediated antibody production, HnrnpL involved in the regulation of TNF α gene transcription." (PMID 35006449, 2021).
sarcoma (1 paper, 2018). A usually aggressive malignant neoplasm of the soft tissue or bone. "Human regulatory proteins HNRNPA1 (heterogeneous nuclear ribonucleoprotein A1), HNRNPC, HNRNPL, HuR (human antigen R), and protein LIN28A (lin-28 homolog A) were predicted to bind ebv-sisRNA-1 and/or ebv-sisRNA-2; FUS (fused in sarcoma) was predicted to associate with ebv-sisRNA-2." (PMID 29458410, 2018).
uterine corpus endometrial carcinoma (1 paper, 2020). A endometrial carcinoma (disease) that involves the body of uterus. "HNRNPM, HNRNPUL1, and HNRNPL showed high mutation frequencies, and most hnRNP genes were frequently mutated in uterine corpus endometrial carcinoma (UCEC)." (PMID 32915499, 2020).